INS (insulin)
Diseases named in the same sentence as INS in open-access papers (continued):
Sharing a sentence is not in itself a finding about the gene and the disease.
Insulin resistance (continued). "Thus, IL‐1β is capable of impairing insulin signalling and action in hepatocytes and thus could participate in the development of hepatic insulin resistance." (PMID 36101976, 2022). "The insulin resistance that developed in concordance with developing hypoglycemia may represent a downstream defense response, preventing any further lowering of the blood sugar by insulin." (PMID 36548717, 2022). "Additionally, the effect of E2 on insulin sensitivity was reported to be dose‐dependent since an excess or a lack of E2 was observed to be associated with insulin resistance in OVX rats." (PMID 35238495, 2022). "Collectively, our data support a role for MAIT cells in the development of metabolic dysfunction, and suggest that an IL-17-mediated effect on intracellular insulin signalling may be involved in driving this dysfunction, potentially highlighting a novel therapeutic target for insulin resistance." (PMID 35305128, 2022). "That is, the mechanism of HBP-induced skeletal muscle insulin resistance is that the increased O-GlcNAcylation of participants in insulin signaling disrupts the balance of its antagonism with phosphorylation on these proteins to negatively regulate insulin signaling." (PMID 36295790, 2022). "In states of insulin resistance, osteoblasts may also be resistant to insulin signaling." (PMID 36278482, 2022). "Furthermore, GLUT protein, which plays a crucial role in opening the glucose channels in the plasma membrane during insulin-mediated glucose uptake, is inhibited under the upregulation of miR-222, leading to insulin resistance and further T2D or GDM complications." (PMID 36078079, 2022). "It has been reported that tau can regulate insulin signaling, and the lack of tau could be the cause of the insulin resistance observed in our system." (PMID 35264925, 2022). "In addition, hyperinsulinemia induced by insulin resistance may increase fat due to the anabolic effect of insulin." (PMID 35355553, 2022). "Moreover, exogenous insulin administration may aggravate β-cell dysfunction, leading to the development of peripheral insulin resistance and diabetic complications." (PMID 36297643, 2022). "However, it is insulin resistance, rather than absolute insulin levels, that underlies the pathophysiology of type 2 diabetes (T2DM)." (PMID 35669689, 2022). "Given that pioglitazone is insulin-sensitizing and iron overload has been shown to result in insulin resistance in the heart, pioglitazone’s interaction with MitoNEET and potential involvement in mitochondrial iron regulation may be a basis of part of its therapeutic impact." (PMID 36611912, 2022). "In this study, we sought to determine if curcumin supplementation during a nutrient stressor known to cause insulin resistance in aged mice might be beneficial to preserving hepatocytes in an insulin-sensitive phenotype while protecting β -cells from the need to compensate for insulin resistance." (PMID 35017319, 2022). "In this paper, we present a randomized controlled trial protocol comparing an intervention group with a control group to determine whether mHealth-based exercise is effective in normalizing insulin sensitivity in HCC patients with insulin resistance after anticancer treatment." (PMID 36348422, 2022). "As ectopic lipid accumulation in the liver closely correlates with insulin resistance and its decrease improves insulin sensitivity, our data suggest that increased liver insulin sensitivity after MitoTam administration could be in part responsible for its glucose-lowering effects." (PMID 35387987, 2022). "However, how insulin affects cellular energy metabolism via long-term transcriptional regulation and whether boosting mitochondrial function alleviates insulin resistance remains to be elucidated." (PMID 35440636, 2022). "Consequently, the insufficient insulin secretion may further increase blood glucose, which will eventually aggravate insulin resistance repeatedly, forming a vicious circle." (PMID 35936373, 2022).
Insulin resistance (continued). "Notably, our finding that insulin resistance may be an important mediating mechanism warrants further attention, as affordable and safe treatments are available to increase insulin sensitivity." (PMID 35104295, 2022). "Interestingly, one such genetic variant (the C allele of rs2943641) present in close proximity to IRS1 is associated with hyperinsulinemia and insulin resistance by negatively impacting the basal IRS1 levels and impairing insulin signaling in human skeletal muscle biopsy samples." (PMID 35842608, 2022). "Additionally, FAT10 has been shown to have a role in regulating autophagy and insulin signaling, which may contribute to its role in the development of inflammation and insulin resistance." (PMID 36386217, 2022). "Interestingly, preclinical studies show that the loss of some beneficial bacteria, such as Akkermansia muciniphila, causes impaired intestinal integrity and systemic inflammation, leading to insulin resistance, while the increased abundance of this bacterium restores normal insulin response." (PMID 35634505, 2022). "According to a previous study and the results of this study, insulin secretion and insulin resistance may indirectly induce an increased length gain, while increasing insulin resistance, which is affected by the excessive secretion of insulin, is one of the inhibitory factors of growth." (PMID 35215391, 2022). "However, they reported impaired glucose tolerance test (35.2%), elevated fasting insulin (41.2%), high glucose-insulin ratio (47.1%), and elevated insulin resistance (47.1%) in 17 patients with myositis (16 children with JDM with a mean of 38 months of active disease)." (PMID 35814777, 2022). "However, severe hyperglycemia is related to both insulin secretion and insulin resistance." (PMID 35673632, 2022). "On the other hand, it is recognized that the TyG index specifically reflects muscle-related insulin resistance, the explanation of which may be that increased triglyceride level in the blood tends to suppress insulin activity in muscle and interfere with glucose uptake." (PMID 36601005, 2022). "High plasma levels of non-esterified fatty acids (NEFA) are known to cause insulin resistance, but the prolonged exposure of pancreatic ß-cells to high fatty acid levels also impairs the insulin-producing capacity of these cells by a process that likely involves the generation of oxidative stress." (PMID 35159354, 2022). "Furthermore, the fasting serum insulin level is an important indicator of insulin resistance." (PMID 35407029, 2022). "Furthermore, the work showed that on the one hand, leptin and insulin influence the risk of PE independently of obesity, but on the other hand, leptin, fasting insulin, and insulin resistance each mediated between 20% and 50% of the total genetically predicted association of obesity with PE." (PMID 36556383, 2022). "Besides, TNF-α can interfere with insulin signaling, leading to insulin resistance." (PMID 35600387, 2022). "Therefore, the presence of insulin resistance implies the existence of an inappropriate effect of the hormone on glucose homeostasis and other metabolic targets such as inhibition of lipolysis but neglects many other facets of insulin action." (PMID 36289636, 2022). "JNK is a critical mediator of insulin resistance, which leads to NASH through dysregulated lipolysis causing excessive transmit of fatty acids to the liver and intracellular accumulation of toxic lipid products that impair insulin signaling and activate inflammatory pathways." (PMID 35528835, 2022). "Given that the levels of blood glucose during pregnancy may reflect the severity of insulin secretory defects and/or insulin resistance during GDM pregnancy, we hypothesized that suboptimal glycemic control in women with GDM would impart an increased risk of postpartum T2DM or prediabetes." (PMID 34996380, 2022).
Insulin resistance (continued). "In addition, two factors may contribute to the increase in gluconeogenesis in MELAS syndrome: insulin resistance, which results in reduced insulin inhibition of hepatic gluconeogenesis, and lactic acidemia, which may fuel hepatic gluconeogenesis." (PMID 36005129, 2022). "However, insulin resistance can be any impairment of insulin action on target tissues." (PMID 36324618, 2022). "Thus, two questions arise: how does insulin affect macrophage function, and could the insulin-dependent modulation of macrophage function be affected by hyperinsulinemia or insulin resistance in macrophages?" (PMID 35955975, 2022). "Studies have confirmed that a low-grade systematic inflammation precedes insulin resistance and could contribute to failure of β–cells; nevertheless, defective insulin signaling pathways in maternal adipose and skeletal muscle tissues amplify insulin resistance." (PMID 35408874, 2022). "This might explain the decrease in blood sugar, hemoglobin A1c, insulin, and insulin resistance." (PMID 36012935, 2022). "Circulating IL-6 contributes to the development of atherosclerosis and insulin resistance, the latter being caused by IL-6-induced impairment of the phosphorylation of insulin receptor and insulin receptor substrate-1 by inducing the expression of SOCS-3, a potential inhibitor of insulin signaling." (PMID 35276970, 2022). "The disinhibition of lipolysis commonly seen in obesity-related insulin resistance (a condition characterized by high insulin levels that fail to exert their action due to receptor resistance) could be mediated - at least in part—by reduced Angptl3 concentrations." (PMID 34951653, 2022). "Thus, insulin resistance induced by long-term insulin exposure may be responsible for dampening or even reversing insulin response." (PMID 35974022, 2022). "It is known that TNFα directly impairs insulin signaling through inhibition of tyrosine kinase activity of the insulin receptor and thus could be a critical mechanism whereby adiposity induces peripheral insulin resistance." (PMID 36364884, 2022). "These degenerative effects exerted by streptozotocin on pancreatic β-cells could be explained by its potential to generate reactive oxygen species (ROS) inside the β-cells and over-production of insulin from the pancreatic beta cells to compensate for insulin insufficiency due to insulin resistance." (PMID 35078449, 2022). "In addition, insulin resistance could result in a defect in insulin-mediated thermogenic response which contributes to the pathogenesis of obesity in humans." (PMID 36012714, 2022). "However, as mentioned, their increased insulin levels point to insulin resistance, and a pyruvate tolerance test (PTT) showed higher substrate-induced hepatic glucose production in SAC mice than in CT mice, even in the presence of significantly higher levels of insulin during the test." (PMID 36611962, 2022). "Insulin resistance is usually caused due to impairment in the signaling pathways related to insulin so that the target tissues pose lesser, or no, response to circulating insulin." (PMID 35807304, 2022). "Insulin resistance (IR) refers to the decline in the efficiency of insulin promoting glucose uptake and utilization for various reasons, and the body's compensatory secretion of excessive insulin produces hyperinsulinemia to maintain the stability of blood glucose." (PMID 35175162, 2022). "As GPx1 KO mice fed an obesogenic diet show decreased adiposity with unaltered insulin sensitivity and GPx1 overexpression causes obesity and insulin resistance, GPx1 function in adipose tissue might not explain the differences between studies." (PMID 35624726, 2022). "Insulin resistance is defined as a decreased ability of insulin to carry out these metabolic actions inherent in glucose uptake and production and lipolysis, thus leading to compensatory high insulin levels, both at baseline and after glucose loading, if pancreatic function is normal." (PMID 35456928, 2022).
Insulin resistance (continued). "Furthermore, a randomized controlled trial identified that colchicine significantly improved obesity-associated inflammatory variables and showed an improvement in fasting insulin resistance, with trends toward improving fasting glucose, fasting insulin, and insulin-independent glucose disposal." (PMID 35329085, 2022). "Nonetheless, the underlying regulatory mechanisms dictating the composition of the plasma lipidome appear to be altered in the metabolically impaired animals as insulin resistance develops, ahead of loss in insulin sensitivity, well in advance of IFG, and independent of differences in adiposity." (PMID 35705631, 2022). "Furthermore, insulin resistance is associated with a significant increase in CVD incidence and mortality, and therefore the high insulin sensitivity (e.g., as seen in the albumin knockout mouse) may be protective from CVD." (PMID 35238481, 2022). "GLP‐1 agonists may facilitate insulin entry in the brain, reduce insulin resistance, decrease neuroinflammation and restore neurogenesis in the absence of elevated peripheral inflammation suggesting that they may be useful in the treatment of non‐diabetic AD patients." (PMID 35128745, 2022). "HCT can contribute to the release of several proinflammatory cytokines such as interleukin-6 (IL-6) and tumor necrosis factor-α (TNF-α), and previous studies have shown that the latter could contribute to insulin resistance by influencing the insulin signaling pathway." (PMID 35406580, 2022). "However, two weight loss dietary interventions with a duration > one year showed an improvement in insulin resistance and a decreases in glucose and insulin concentrations in non-risk allele subjects with overweight/obesity." (PMID 36155628, 2022). "Due to insufficient insulin secretion or insulin resistance, insulin-stimulated glucose uptake is markedly reduced in skeletal muscle and a hyperglycemic condition leads to endothelial and cerebral microvascular dysfunction, which may affect both physical performance and cognitive function." (PMID 36157461, 2022). "This long-term exercise-induced decrease in FFM needs to be interpreted in light of the findings of the team of Isabelle Dionne who showed that a greater fat-free mass in sedentary patients is associated with insulin resistance and not with better insulin sensitivity." (PMID 35458167, 2022). "Furthermore, exercise improves insulin sensitivity, even in the setting of insulin resistance." (PMID 35016012, 2022). "A previous study has reported that mice lacking nucleobindin 2 (NUCB2), a precursor of nesfatin involved in appetite regulation, exhibit insulin resistance and high Wdfy1 expression in their visceral macrophages, suggesting that Wdfy1 may be also involved in insulin signaling." (PMID 36548271, 2022). "Therefore, high levels of fasting plasma insulin can reflect insulin resistance." (PMID 35463673, 2022). "This distinction must also be considered in light of current discussions that simple, unitary defects in proximal insulin signaling may not be the primary cause of systemic insulin resistance in type 2 diabetes." (PMID 35789435, 2022). "Thus, oestrogens have been shown to protect against HFD-induced insulin resistance and glucose intolerance in mice and work in oestrogen receptor-α (ERα) knockout mice suggests that oestrogen may improve hepatic insulin sensitivity through ER-α signalling." (PMID 35163366, 2022). "Women with low muscle mass had higher levels of insulin (uIU/mL; β = -0.40; 95% CI: -0.79, -0.01), fasting plasma glucose (mg/dL; β = -0.1; 95% CI: -0.2, 0.03), HbA1c (%; β = -2.30; 95% CI: -5.7, 1.1), and calculated homeostatic model of insulin resistance, HOMA-IR, (β = -1.49; 95% CI: -2.9, -0.1)." (PMID 36490255, 2022).
Insulin resistance (continued). "This prospective, single-center, randomized, double-blinded, placebo-controlled trial suggests that UC-MSCs administration via intravenous infusion is a safe and effective approach that could reduce exogenous insulin requirement and could alleviate insulin resistance in patients with T2DM." (PMID 35505375, 2022). "Research has shown that transcriptional responses linked to impairment of muscle insulin signalling were not evident after a single day of bed rest, but mRNA expression was markedly changed after 9‐day bed rest and was associated with insulin resistance in healthy men." (PMID 36058634, 2022). "Hyperinsulinemia is present in T2D due to insulin resistance, and supraphysiological levels are hypothesized to amplify insulin’s mitogenic effect, both through direct receptor activation and an increase in IGF-1 signaling, promoting the proliferation of malignant cells." (PMID 36139140, 2022). "Considering the role of neuroinflammation in insulin resistance and the role of the components involved in insulin signaling transduction mediating inflammatory processes, it could be deduced that neuroinflammation may facilitate the crosstalk between insulin dysfunction and PD." (PMID 35615716, 2022). "Although the role of resistin in obesity and insulin resistance in humans is still highly debated, it has been found that resistin levels are higher in obese subjects than control subjects and significantly correlated with high adiposity and low insulin sensitivity." (PMID 35628332, 2022). "Relatively recent studies have shown that the Tg/HDL cholesterol ratio represents a good marker of insulin resistance in a multi-ethnic cohort of obese and overweight children being associated with both OGTT (Oral Glucose Tolerance Test) and clamp derived measures of insulin sensitivity." (PMID 35139895, 2022). "Interestingly, the component related to insulin resistance, as detected by fasting insulin levels, was independently associated with F8, but not with vWF nor with F8/PC." (PMID 36313186, 2022). "The role of insulin and inflammatory cytokine signaling in regulating liver, adipose, and skeletal muscle sortilin stability suggests that inflammation and impaired insulin signaling (insulin resistance) contribute to reduced sortilin protein in these tissues in obesity." (PMID 35724703, 2022). "Indeed, obesity leads to insulin resistance with increased insulin and IGF-1 and hyperandrogenism." (PMID 35276950, 2022). "Patients receiving OLA exhibited significantly higher insulin and glucose levels than those receiving conventional antipsychotics, indicating that OLA has a direct stimulating role on insulin secretion from pancreatic beta cells, or may simultaneously act secondary to insulin resistance." (PMID 35800023, 2022). "However, chronic hyperinsulinaemia, which is present in insulin resistant mothers and corresponds to high insulin levels in the fetus, might induce insulin resistance in the fetal brain." (PMID 35258482, 2022). "Autophagy suppression may not affect insulin signaling transduction via phosphatase expression but indirectly causes insulin resistance through ER stress or apoptosis." (PMID 35990905, 2022). "Correlation analysis showed substantial differences in interactions among lipid species in insulin resistant animals compared to healthy controls, pointing to differences in lipid handling, including elongation and desaturation, early in the development of insulin resistance." (PMID 35705631, 2022). "Therefore, oxidative stress-induced damage of BVR-A may turn-off the activation of insulin signaling, diminishing its neuroprotective effects before a frank brain insulin resistance develops." (PMID 35628384, 2022). "We used crude measures of insulin sensitivity/insulin resistance, which may be less accurate." (PMID 35103244, 2022).